PRRT4 (proline rich transmembrane protein 4)
Tractability: Antibody: UniProt predicts a signal peptide or a membrane-spanning region; the Human Protein Atlas places it where antibodies can reach. PROTAC: ubiquitination databases record sites on it.
Gene: Protein-coding gene on chromosome 7 (128,350,325 to 128,361,690, reverse strand). Ensembl gene ENSG00000224940.
Subcellular location: Membrane
Subcellular location (Human Protein Atlas): Nucleoplasm; Peroxisomes; Plasma membrane
Gene Ontology:
Cellular component: membrane
Genetic constraint (gnomAD): Loss-of-function variants: 59 observed, 40.55 expected, observed/expected ratio (o/e) 1.45, 90% interval 1.18 to 1.79. The synonymous counts are far from expectation, so gnomAD's model fits this gene poorly and the ratio says little. Missense variants: 1,217 observed, 993.35 expected, observed/expected ratio (o/e) 1.23, 90% interval 1.17 to 1.28. Synonymous variants: 606 observed, 484.41 expected, observed/expected ratio (o/e) 1.25, 90% interval 1.17 to 1.34.
Homologues: Orthologues: chimpanzee PRRT4 (99% identical), macaque PRRT4 (95% identical), pig PRRT4 (88% identical), dog PRRT4 (87% identical), rabbit PRRT4 (86% identical), rat Prrt4 (85% identical), guinea pig PRRT4 (85% identical), mouse Prrt4 (85% identical), tropical clawed frog prrt4 (28% identical), zebrafish prrt4b (27% identical), zebrafish prrt4a (24% identical).
Diseases named in the same sentence as PRRT4 in open-access papers:
PRRT4 is named in the same sentence as 2 diseases in open-access papers, as found by Europe PMC text mining. Sharing a sentence is not in itself a finding about the gene and the disease. The quoted sentences say what the papers report.
gastric cancer (1 paper, 2023). A primary or metastatic malignant neoplasm involving the stomach. "PRRT4 is considered a new prognostic biomarker for gastric cancer." (PMID 36816364, 2023).
PRRT4 also shares sentences with these, for which no sentence is quoted: cancer (1 paper).